CRP (C-reactive protein)
Diseases named in the same sentence as CRP in open-access papers (continued):
Sharing a sentence is not in itself a finding about the gene and the disease.
periodontitis (continued). "Univariate Cox analysis and Gompertz models, selected based on AIC and BIC after evaluating alternative models, were employed to assess the predictive roles of CRP and eGFR in periodontitis incidence, adjusting for oral and systemic health factors." (PMID 39859455, 2025). "Systemic inflammation, commonly reflected by biomarkers such as C-reactive protein (CRP) and white blood cell count (WBC), has been implicated in both the onset and progression of periodontitis." (PMID 40880748, 2025). "Cytokines, including TNF-α, CRP, IL-6, IL-17, IL-8 and IFN-γ, are associated with periodontitis and gestational diabetes mellitus." (PMID 41394354, 2025). "Periodontal tissues of patients with periodontitis show increased production of inflammatory cytokines and elevated levels of inflammatory markers such as C-reactive protein, tumor necrosis factor-alpha, and interleukin-6 in the blood." (PMID 40076415, 2025). "CRP is elevated in the gingival crevicular fluid in the presence of local oral inflammation, such as gingivitis or periodontitis." (PMID 40871545, 2025). "The majority of CRP originates from the liver, but CRP and IL-6 mRNAs have been detected in gingival tissue samples from periodontitis patients." (PMID 40871545, 2025). "This relationship seems reversible as effective treatment of periodontitis results in a normalization of some inflammatory biomarkers, including CRP." (PMID 39737182, 2024). "A relatively large number of clinical cross‐sectional studies and periodontal treatment studies have been carried out to assess plasma/serum CRP, and plasma fibrinogen in peripheral blood in healthy individuals and patients with periodontitis." (PMID 39494478, 2024). "It specifically focuses on the levels of interleukin-6 (IL-6), lactate dehydrogenase (LDH), and C-reactive protein (CRP) in those suffering from chronic periodontitis compared to healthy controls." (PMID 38595889, 2024). "The lower levels of Adiponectin and higher levels of CRP and MIP-1α in patients with periodontitis indicate that this condition is a potential risk factor for cardiovascular disease." (PMID 38433948, 2024). "An increased white blood cell count, and an elevated CRP level are expected to be a response to periodontitis, which occurs as part of the inflammatory cascade." (PMID 39797107, 2024). "The interactive effect was estimated; the synergistic effect of CRP levels and periodontitis status on mortality was assessed using the relative excess risk due to interaction (RERI)." (PMID 39453923, 2024). "Results indicated that patients with periodontitis had significantly higher levels of IL-6, LDH, and CRP compared to the control group, highlighting an association between elevated biomarker levels and periodontitis." (PMID 38595889, 2024). "Patients with periodontitis exhibited elevated CRP levels, whereas those with gingivitis demonstrated elevated gamma-glutamyl transferase (GGT) levels." (PMID 39100036, 2024). "Recent evidence indicates that CRP involves in the regulation of alveolar bone homeostasis in periodontitis." (PMID 38229065, 2024). "The impact of periodontitis on systemic health can be assessed by biomarkers such as C-reactive protein, leukocyte counts, especially neutrophils, red blood cell count, haemoglobin, and various cytokines levels measured in the peripheral blood." (PMID 39797107, 2024). "The eGFR was significantly lower but the CRP level was higher in the periodontitis group than those in the non-periodontitis group." (PMID 39453923, 2024). "Levels of IL-6, LDH, and CRP in those suffering from chronic periodontitis compared to healthy controls were checked." (PMID 38595889, 2024). "The most important basis of the strong connection between periodontitis and AD is inflammation which is expressed in terms of pro-inflammatory mediators mainly the CRP." (PMID 38196480, 2024).
periodontitis (continued). "Other studies have shown that serum CRP levels and fibrinogen are significantly increased in acute coronary syndrome patients, including those with periodontitis." (PMID 38433948, 2024). "CRP and S100A8 were chosen as relevant markers of systemic inflammation associated with both periodontitis and CVD." (PMID 38667035, 2024). "The accumulated data indicate that periodontitis in ESRD patients is a potential risk factor for increased serum CRP levels, and, moreover, that effective periodontal treatment can decrease serum CRP levels." (PMID 39396133, 2024). "Ur Rahman et al6 showed that CRP levels in the serum of patients with periodontitis were higher than normal." (PMID 39027205, 2024). "Patients with severe periodontitis had higher blood neutrophil counts and pro-inflammatory mediator levels (such as IL-1, IL-6, CRP, and fibrinogen) compared to healthy controls, which were associated with a higher cardiovascular risk." (PMID 38877442, 2024). "The additive scale interactive effect between periodontitis status and CRP levels was positive and nearly significant in the total population." (PMID 39453923, 2024). "Administration of curcumin has additionally been demonstrated to reduce other biomarkers of periodontitis, including C-reactive protein (CRP), alkaline phosphatase (ALP), and procalcitonin (PCT)." (PMID 39912085, 2024). "The concentration of CRP is consistently elevated in patients with periodontitis in comparison to healthy controls." (PMID 39203574, 2024). "Recent studies have suggested potential links between periodontitis during pregnancy and systemic inflammatory markers such as CRP, IL-6, and TNF-α." (PMID 38595889, 2024). "This systematic review and meta-analysis confirmed that plasma CRP levels in patients with periodontitis are higher than those in healthy controls and that periodontal treatment can partially reduce CRP levels." (PMID 39610974, 2024). "For further analysis, the participants were grouped into the mild, moderate, and severe groups according to the severity of periodontitis and CRP levels." (PMID 39453923, 2024). "Periodontitis is related to increased CRP levels resulting from the acute-phase response to inflammation." (PMID 39396133, 2024). "The expression levels of adiponectin, MIP-1 alpha, and CRP significantly varied between MI patients with periodontitis, patients with periodontitis, and controls." (PMID 38433948, 2024). "Recent studies have explored the potential impact of periodontitis during pregnancy on systemic inflammatory markers such as CRP, IL-6, and tumor necrosis factor-alpha (TNF-α)." (PMID 38595889, 2024). "Compared to healthy controls, patients with severe periodontitis and elevated levels of proinflammatory mediators, such as interleukin-1, interleukin-6, C-reactive protein, and fibrinogen, also had increased neutrophils count in the peripheral blood." (PMID 38968002, 2024). "Proteomic analysis has revealed that chronic periodontitis induces systemic inflammation characterized by elevated levels of pro-inflammatory cytokines such as interleukin-6 (IL-6) and C-reactive protein (CRP)." (PMID 38892299, 2024). "The chronic elevation of CRP levels in patients with periodontitis serves to exacerbate the inflammatory processes that occur within atherosclerotic plaques." (PMID 39203574, 2024). "Systemically healthy subjects with localised or generalised periodontitis (stage III, grade C) were included in the study in order to increase the accuracy of CRP-level measurment and systemic burden caused by periodontal disease." (PMID 38652288, 2024). "In the subpopulation analysis, the synergy between periodontitis status and CRP levels was more prominent in individuals aged ≥60 years." (PMID 39453923, 2024).
periodontitis (continued). "Recent studies have highlighted the roles of galectin-3, Nod-like receptor pyrin domain-containing protein-3 (NLRP3), and soluble urokinase-type plasminogen activator receptor (suPAR) in periodontitis progression and their interactions with CRP." (PMID 39453923, 2024). "Bacterial lipopolysaccharides released into the bloodstream of patients with chronic infections such as periodontitis induce the production of acute phase proteins such as C-reactive protein (CRP)." (PMID 39203574, 2024). "Despite undiagnosed periodontitis, the CRP values of the NPG were above this value for healthy individuals." (PMID 38535432, 2024). "This study aimed to evaluate the levels of MIP-1 alpha, adiponectin, and CRP in unstimulated whole saliva from 60 adult subjects grouped as healthy, stage 3 periodontitis, and post-AMI subjects with stage 3 periodontitis." (PMID 38433948, 2024). "Inflammatory mediators released because periodontitis can stimulate the production of CRP from hepatocytes." (PMID 38195732, 2024). "Potential biomarkers linking periodontitis to endothelial dysfunction, such as CRP, ICAM-1, IL-1, E-selectin, vWF, and PAT-1, have been found to decrease after periodontal treatment." (PMID 39203574, 2024). "Periodontitis induces the release of inflammatory mediators that stimulate hepatocytes to produce CRP." (PMID 39453923, 2024). "Among the inflammation biomarkers studied in relationship to periodontitis, serum C-reactive protein (CRP) is the most commonly examined." (PMID 39105056, 2024). "Clinical evidence confirms that patients with periodontitis exhibit elevated levels of pro-inflammatory mediators, including IL-1β, IL-6, TNFα, and C-reactive protein (CRP), as well as increased neutrophil counts in peripheral blood when compared to controls." (PMID 39737182, 2024). "Salivary CRP levels were significantly elevated in MI patients with periodontitis, followed by periodontitis patients and then controls." (PMID 38433948, 2024). "Relative excess risk due to interaction-based assessment of the synergistic effects of C-reactive protein level and periodontitis status on mortality." (PMID 39453923, 2024). "A study by our group proved that CRP levels in GCF were statistically elevated in women with periodontal diseases and correlated with CRP detected in serum in all study groups (periodontitis, gingivitis, and controls)." (PMID 39795606, 2024). "We were unable to compare the performance of SII with CRP in predicting periodontitis in adults aged 50 or older due to the missing CRP data for 2011–2014 from the national periodontitis surveillance project NHANES 2009–2014." (PMID 38263194, 2024). "Measurement of CRP is a useful tool to monitor the activity of chronic inflammatory diseases such as RA and periodontitis." (PMID 38248363, 2024). "Dampening the hepatic systemic response due to a reduction of local inflammatory cytokines is the most plausible mechanism explaining a reduction of CRP after treatment of periodontitis." (PMID 39737182, 2024). "The study underscored a clear link between higher levels of IL-6, LDH, and CRP and the presence of chronic periodontitis in pregnant women." (PMID 38595889, 2024). "Our results showed that CRP levels were significantly elevated in the saliva of both MI and periodontitis patients compared to healthy controls, consistent with previous research reporting elevated CRP levels in STEMI patients." (PMID 38433948, 2024). "Although elevated CRP levels in periodontitis have shown greater consistency and significance, data regarding the relationship between pregnancy complications and inflammatory mediator levels in gingival fluid and plasma are limited." (PMID 38672972, 2024). "CRP is a sensitive serological marker of inflammation, and has been posited as a mediator of the relationship between periodontitis and systemic illness." (PMID 39396133, 2024). "Periodontitis results in elevated systemic levels of C- reactive protein, IL-1β, IL-6, IL-8, and TNF-α." (PMID 39917647, 2024).
periodontitis (continued). "También se ha demostrado que la administración de curcumina reduce otros biomarcadores de periodontitis, incluidos proteína C reactiva (CRP), fosfatasa alcalina (ALP) y procalcitonina (PCT)." (PMID 39912085, 2024). "This study uses NHANES 2001–2004 data to elucidate the synergistic impact of periodontitis and elevated CRP levels on mortality." (PMID 39453923, 2024). "Examining the interactive roles between periodontitis and CRP levels is crucial for assessing additional damages in patients with periodontitis and suggesting effective treatment strategies." (PMID 39453923, 2024). "The serum CRP levels are elevated in severe periodontitis, and periodontal therapy can reduce these levels over time." (PMID 39453923, 2024). "A meta-analysis showed that serum C-Reactive protein (CRP) levels were closely related to periodontitis." (PMID 38263194, 2024). "For example, elevated levels of C-reactive protein (CRP), a marker of systemic inflammation, are frequently observed in individuals with periodontitis and are associated with an increased risk of cardiovascular diseases." (PMID 39189252, 2024). "This study aimed to assess the synergistic effects of periodontitis and elevated CRP levels on mortality in 7,938 adult individuals who participated in the National Health and Nutrition Examination Study 2001–2004." (PMID 39453923, 2024). "Periodontal bacterial and related endotoxins, present during periodontitis, trigger systemic inflammation, as revealed by the increased levels of CRP, TNFα, IL-1β, and IL-6 in the serum of patients." (PMID 37895050, 2023). "CRP indicates systemic inflammation and patients with severe periodontitis have been reported to have an increased level in serum." (PMID 37674208, 2023). "Pearson’s correlation coefficient was used to assess the correlation between serum CRP levels and Russell’s index (RI) in group 2 (subjects with moderate periodontitis) at baseline and two months following periodontal treatment." (PMID 38077410, 2023). "CRP, an inflammatory marker known to be associated with CVD is also found to be elevated in patients with chronic and aggressive periodontitis." (PMID 38139161, 2023). "Nonetheless, some potential biomarkers were noticed in the serum of patients with periodontitis, such as resistin, C-reactive protein, visfatin, oncostatin M, chemokine CXCL10, and proprotein convertase subtilisin/kexin type 9 (PCSK9)." (PMID 37535199, 2023). "Two months after periodontal treatment, patients with moderate periodontitis showed a significant reduction in serum CRP level." (PMID 38077410, 2023). "Correlations between CRP/BMI and periodontitis were tested for statistical significance by means of descriptive statistics, multivariate regression, and subgroup-stratified analyses, with and without adjustments for confounders (such as age and sex)." (PMID 37481511, 2023). "Several in-vivo and in-vitro studies of periodontitis have shown that the nervous and immune systems respond to systemic inflammatory responses, increasing interleukin-1, C-reactive protein, tumor necrosis factor, and matrix metalloproteinases." (PMID 37113482, 2023). "Patients with periodontitis also have increased levels of acute-phase agents like C-reactive protein and interleukins along with elevated levels of oxidative stress." (PMID 38150604, 2023). "In regards to periodontitis, it has been well documented that higher CRP levels are found in the saliva and serum of periodontitis patients compared to healthy individuals, and following treatment for periodontitis, CRP levels decrease." (PMID 37568161, 2023). "The relationship between serum CRP levels and periodontitis severity was statistically significant (p = 0.006), which was similar to the findings of the present investigation." (PMID 37575815, 2023). "This enabled us to compare the normal values of serum CRP of periodontally healthy subjects, i.e., control group A to those of chronic periodontitis of test Group B2 following SRP." (PMID 37568846, 2023).
periodontitis (continued). "The level of CRP in the blood is an accepted method of measuring systemic inflammation in individuals, with robust evidence that CRP levels are elevated in clients with periodontitis." (PMID 36833652, 2023). "It evaluated the stages of periodontitis and its correlation to CRP levels as an inflammatory marker and subsequently evaluated the patients' risk for cardiovascular disease." (PMID 37575815, 2023). "Periodontitis severity is related to increased prevalence of Porphyromonas gingivalis, elevated CRP levels, and higher frequencies of circulating CD8 + senescent cells in PLWH." (PMID 36316604, 2023). "Only the CRP levels were significantly higher in the group with severe periodontitis than in the group with moderate periodontitis [1.6 mg/L (IQR 0.9–3.0) versus 0.8 mg/L (IQR 0.5–2.0), respectively, p = 0.02]." (PMID 36316604, 2023). "Inflammatory mediators, such as C-reactive protein and IL-6, are also elevated in the serum of periodontitis patients." (PMID 36873050, 2023). "Common inflammatory phenotypes in oral (e.g., periodontitis) can stimulate the increase in circulating inflammatory factors such as CRP, Interleukin-1, Interleukin-6, and Interleukin-8 as well." (PMID 37978427, 2023). "Excluding smoking and diabetes, along with other confounding factors, the results showed a 65% increase in plasma CRP levels in samples with periodontitis compared with healthy controls." (PMID 37511934, 2023). "Periodontitis triggers a systemic inflammatory response mediated by various factors, including C-reactive protein, interleukin 1b (IL-1b), interleukin 6 (IL-6), tumor necrosis factor alpha (TNF-α), and others." (PMID 38001437, 2023). "C-reactive protein levels are especially higher in patients with periodontitis and cardiovascular disease than healthy patients or patients with either condition." (PMID 36873050, 2023). "The long-term activity of specific bacteria in periodontitis stimulated the secretion of C-reactive protein." (PMID 37803341, 2023). "Patients with moderate periodontitis showed a reduction in serum CRP level followed by periodontal therapy." (PMID 38077410, 2023). "As CRP is a key mediator for cardiovascular disease, an increase in C- reactive protein levels in periodontal diseases suggests a significant connection between periodontitis and cardiovascular diseases." (PMID 38077410, 2023). "Our study emphasizes the previous study concerning the significant effect of IL-6 on increasing CRP levels in chronic periodontitis with CAD." (PMID 37239434, 2023). "We found that IL-6 levels had a significant effect on CRP levels in periodontitis patients with CAD (path coefficient 0.322, p = 0.003)." (PMID 37239434, 2023). "A systematic review evaluated the presence of CRP in patients with periodontitis, showing strong evidence of elevated CRP in patients with periodontitis." (PMID 37568542, 2023). "When serum levels of C-reactive protein for controls Group A were compared to those of periodontitis patients in Group B1, the results were also significant (p < 0.001)." (PMID 37568846, 2023). "Individuals with moderate periodontitis had higher serum CRP levels than those with healthy periodontium." (PMID 38077410, 2023). "A study conducted in Thailand revealed that non-surgical periodontal treatment can reduce serum leptin and C-reactive protein (CRP) levels in periodontitis patients." (PMID 38111655, 2023). "More specifically, GCF-15 and CRP, a growth factor and an acute plasma protein, respectively, have been shown to act as a regulator in the early immune response during periodontitis." (PMID 37605193, 2023). "Chronic periodontitis enhances blood levels of systemic inflammatory markers like CRP, which has been reduced by periodontal treatment with SRP." (PMID 37568846, 2023). "In the chronic and aggressive periodontitis group, mean serum CRP and plasma fibrinogen levels were higher than those in the control group." (PMID 37481511, 2023).